SAXO5 (stabilizer of axonemal microtubules 5)
Synonyms: C19orf45; TEX45; FLJ35784
Tractability: No criterion of Open Targets' tractability assessment is met for any kind of drug.
Gene: Protein-coding gene on chromosome 19 (7,492,976 to 7,508,450, forward strand). Ensembl gene ENSG00000198723.
Subcellular location (Human Protein Atlas): End piece; Mid piece; Principal piece
Gene Ontology:
Molecular function: protein binding
Genetic constraint (gnomAD): Loss-of-function variants: 45 observed, 44 expected, observed/expected ratio (o/e) 1.02, 90% interval 0.81 to 1.31. The upper end of that interval is the gene's LOEUF score, 1.31, which puts it in group 5 of 6, group 1 being the genes least tolerant of losing a copy. Missense variants: 667 observed, 640.5 expected, observed/expected ratio (o/e) 1.04, 90% interval 0.98 to 1.11. Synonymous variants: 292 observed, 274.22 expected, observed/expected ratio (o/e) 1.06, 90% interval 0.97 to 1.17.
Homologues: Orthologues: chimpanzee SAXO5 (98% identical), macaque SAXO5 (79% identical), pig SAXO5 (66% identical), rabbit SAXO5 (65% identical), guinea pig SAXO5 (62% identical), mouse Saxo5 (58% identical), rat Saxo5 (57% identical).
Diseases named in the same sentence as SAXO5 in open-access papers:
SAXO5 is named in the same sentence as 3 diseases in open-access papers, as found by Europe PMC text mining. Sharing a sentence is not in itself a finding about the gene and the disease.
SAXO5 shares sentences with these, for which no sentence is quoted: cancer (1 paper); colorectal cancer (1); tumor (1).